ASTL (astacin like metalloendopeptidase)
Description:
Oocyte-specific oolemmal receptor involved in sperm and egg adhesion and fertilization. Plays a role in the polyspermy inhibition. Probably acts as a protease for the post-fertilization cleavage of ZP2. Cleaves the sperm-binding ZP2 at the surface of the zona pellucida after fertilization and cortical granule exocytosis, rendering the zona pellucida unable to support further sperm binding.
Synonyms: ovastacin; SAS1B; OOMD11; OZEMA11
Tractability: Antibody: UniProt places it where antibodies can reach, with medium confidence; UniProt predicts a signal peptide or a membrane-spanning region; its Gene Ontology location is reachable by antibodies, with medium confidence.
Gene: Protein-coding gene on chromosome 2 (96,122,818 to 96,138,564, reverse strand). Ensembl gene ENSG00000188886.
Subcellular location: Cytoplasm; Cell membrane; Cytoplasmic vesicle, secretory vesicle, Cortical granule
Gene Ontology:
Molecular function: protein binding; aspartic-type peptidase activity; glutamic-type peptidase activity; metalloendopeptidase activity; metallopeptidase activity; peptidase activity; zinc ion binding
Biological process: cell adhesion; fertilization; negative regulation of binding of sperm to zona pellucida; positive regulation of protein processing; prevention of polyspermy; proteolysis
Cellular component: cortical granule; cytoplasm; plasma membrane
Genetic constraint (gnomAD): Loss-of-function variants: 26 observed, 35.23 expected, observed/expected ratio (o/e) 0.74, 90% interval 0.54 to 1.02. The upper end of that interval is the gene's LOEUF score, 1.02, which puts it in group 4 of 6, group 1 being the genes least tolerant of losing a copy. Missense variants: 517 observed, 569.71 expected, observed/expected ratio (o/e) 0.91, 90% interval 0.84 to 0.98. Synonymous variants: 222 observed, 229.52 expected, observed/expected ratio (o/e) 0.97, 90% interval 0.87 to 1.08.
Homologues: Orthologues: chimpanzee ASTL (98% identical), macaque ASTL (93% identical), guinea pig ASTL (73% identical), dog ASTL (71% identical), rat Astl (70% identical), mouse Astl (68% identical), pig ASTL (68% identical), tropical clawed frog astl (42% identical), Drosophila melanogaster CG6696 (23% identical), zebrafish hce2l2 (23% identical), Drosophila melanogaster CG10280 (22% identical), Drosophila melanogaster CG5715 (22% identical), and 2 more. Paralogues in human: MEP1B (23% identical), TLL1 (21% identical), BMP1 (21% identical), TLL2 (21% identical), MEP1A (20% identical), CNTNAP5 (19% identical), CNTNAP4 (19% identical), CNTNAP2 (19% identical), CNTNAP3 (19% identical), CNTNAP3B (19% identical), CUBN (18% identical), CNTNAP1 (18% identical), and 23 more.
Diseases named in the same sentence as ASTL in open-access papers:
ASTL is named in the same sentence as 21 diseases in open-access papers, as found by Europe PMC text mining. Sharing a sentence is not in itself a finding about the gene and the disease. The quoted sentences say what the papers report.
female infertility (4 papers, 2023 to 2025). Diminished or absent ability of a female to achieve conception. "One study identified a point mutation within the ASTL gene in two siblings causing exon 6 skipping, which is associated with female infertility." (PMID 40697826, 2025). "Other point mutations in the human ASTL gene, leading to single amino acid exchange within the catalytic domain, have also been described to cause female infertility." (PMID 40697826, 2025). "ASTL is an ovastacin enzyme that is responsible for cleaving ZP2 to prevent polyspermy and has been linked to female infertility." (PMID 40073759, 2025). "Thus, given the potential impact of ASTL on female infertility, it becomes imperative to study changes in the ASTL gene which can be brought about by non-synonymous single nucleotide polymorphisms (nsSNPs) and have not yet been looked into." (PMID 37363721, 2023).
uterine tumor (3 papers, 2015 to 2018). "RNA samples from 38 uterine tumor specimens and 8 normal uterine biopsy tissues were converted to cDNAs and screened for SAS1B transcripts using C-term ASTL primers." (PMID 26327203, 2015). "Based on this information, the current study was undertaken to investigate the frequency of ASTL transcription and translation in an exploratory cohort of uterine tumors and to evaluate if SAS1B might offer opportunities as a target for a novel immunotherapeutic approach." (PMID 26327203, 2015).
pancreatic cancers (2 papers, 2018 to 2024). "Here we characterize SAS1B (ovastacin, ASTL, astacin-like), a cancer-oocyte antigen, as an attractive immunotoxin target expressed at the surface of human pancreatic cancer cells, with limited expression among normal tissues." (PMID 29507667, 2018).
uterine cancer (2 papers, 2015 to 2018). Primary or metastatic malignant neoplasm involving the uterine corpus and/or the cervix. "Given the expression of ASTL (gene)/SAS1B (protein) in uterine cancer, we hypothesized that ASTL/SAS1B may be expressed in PDAC." (PMID 29507667, 2018).
breast carcinoma (1 paper, 2017). "Top HBF + BPA-dysregulated genes (ALDH1B1, ASTL, CA7, CPLX4, KCNV2, MAGEE2 and TUBA3E) are associated with poor overall survival in The Cancer Genomic Atlas (TCGA) human breast cancer cohort (n = 1082)." (PMID 28487351, 2017). "To gain clinical significance, using The Cancer Genomic Atlas (TCGA) breast cancer cohort, we dichotomized 1082 breast cancer subjects into two groups based on the expression of the seven genes (ALDH1B1, ASTL, CA7, CPLX4, KCNV2, MAGEE2 and TUBA3E)." (PMID 28487351, 2017). "We took advantage of the publicly available RNA-seq and survival data from TCGA and determined that seven differentially expressed genes (ALDH1B1, ASTL, CA7, CPLX4, KCNV2, MAGEE2 and TUBA3E) could be involved in breast cancer development, especially in Caucasian female patients with ER positivity." (PMID 28487351, 2017). "Interestingly, expression of four genes (ALDH1B1, ASTL, CA7 and TUBA3E) of the seven gene panel was significantly different between the two groups of human breast cancer subjects (data not shown)." (PMID 28487351, 2017).
cyst (1 paper, 2013). A sac-like closed membranous structure that may be empty or contain fluid or amorphous material. "ASTL was decreased in the malignant cyst fluid compared to the benign, and was detected in three sets with 1–3 peptides in each set." (PMID 23557354, 2013). "The external validation of 68 cyst fluids revealed a significant but reverse relationship between the expression of ASTL and malignancy compared to iTRAQ data." (PMID 23557354, 2013). "Unexpectedly, the cyst fluid levels of ASTL were significantly higher in malignant cyst fluids (p = 0.003)." (PMID 23557354, 2013). "Two proteins, serum amyloid A-4 (SAA4) and astacin-like metalloendopeptidase (ASTL), were selected for verification of the iTRAQ method and external validation with immunoblot in a larger cohort with mixed histology, in plasma (n = 68), and cyst fluid (n = 68)." (PMID 23557354, 2013).
Infertility (1 paper, 2023). "In light of the recent research associating a truncated variant of ASTL with infertility, and the observation of altered fertility in ASTL−/− and FETUB−/− female mice, we conducted an analysis of nsSNPs and regulatory SNPs in ASTL from the dbSNP database." (PMID 37363721, 2023). "Lack of FETUB binding to ASTL can also cause infertility, hence docking studies of ASTL with its inhibitor were performed to see if any of the identified ASTL SNPs were affecting the binding of FETUB and hence fertility." (PMID 37363721, 2023). "Pre-mature release of ASTL when FETUB is absent also causes infertility." (PMID 37363721, 2023). "Any perturbation in the activity of ASTL can thus disturb this process and may lead to infertility without changing the gross morphology of the oocyte." (PMID 37363721, 2023). "Additionally, the structural data can be utilized to discover specific small-molecule inhibitors of ASTL that may be useful in the treatment of infertility in cases FETUB is non-functional or, in reducing failures in ART techniques like in vitro fertilization." (PMID 37363721, 2023).
malignant mixed Mullerian tumors (1 paper, 2015). "Gene-specific PCR and immunohistochemical studies revealed ASTL messages and SAS1B protein in both endometrioid [74%] and malignant mixed Mullerian tumors (MMMT) [87%] of the uterus." (PMID 26327203, 2015).
metastatic tumors (1 paper, 2018). "Correlation of ASTL/SAS1B expression with patient data showed that ASTL/SAS1B expression occurs in tumors from both males and females, tumors of early and late stage (II to IV), as well as in primary and metastatic tumors." (PMID 29507667, 2018).
ovarian carcinoma (1 paper, 2013). A malignant neoplasm originating from the surface ovarian epithelium. "ASTL had the largest fold change and it has previously been associated with expression in the ovary and ovarian carcinomas." (PMID 23557354, 2013).
tumor (4 papers, 2015 to 2024). "A change was observed in the biochemical parameters of blood only in mice bearing A549 tumours, whereas in combined treatment groups, a decrease in the levels of ASTL, CRE2, UREL and ALB was noticed." (PMID 35701366, 2022). "SAS1B was detected in permeabilized ASTL mRNA+ tumor cells throughout the cytoplasm and was concentrated in the perinuclear endoplasmic reticulum/Golgi region." (PMID 26327203, 2015).
ASTL also shares sentences with these, for which no sentence is quoted: cancer (4 papers); Endometrial tumors (1); endometrioid adenocarcinoma (1); endometrioid tumor (1); lung adenocarcinoma (1); lung carcinoma (1); melanoma (1); renal cell carcinoma (1); serous papillary carcinoma (1); squamous cell lung carcinoma (1).